GIGYF1 (GRB10 interacting GYF protein 1)
Description:
May act cooperatively with GRB10 to regulate tyrosine kinase receptor signaling. May increase IGF1 receptor phosphorylation under IGF1 stimulation as well as phosphorylation of IRS1 and SHC1 (By similarity).
Synonyms: PERQ1; GYF1
Tractability: PROTAC: ubiquitination databases record sites on it; its protein half-life has been measured.
Gene: Protein-coding gene on chromosome 7 (100,679,505 to 100,694,480, reverse strand). Ensembl gene ENSG00000146830.
Subcellular location (Human Protein Atlas): Vesicles; Basal body; Microtubules; Mitotic spindle; Primary cilium
Gene Ontology:
Molecular function: protein binding
Biological process: insulin-like growth factor receptor signaling pathway; negative regulation of translational initiation; pre-mRNA catabolic process
Cellular component: protein-containing complex; cytosol
Genetic constraint (gnomAD): Loss-of-function variants: 84 observed, 137.02 expected, observed/expected ratio (o/e) 0.61, 90% interval 0.51 to 0.74. The synonymous counts are far from expectation, so gnomAD's model fits this gene poorly and the ratio says little. Missense variants: 1,485 observed, 1,350.9 expected, observed/expected ratio (o/e) 1.1, 90% interval 1.05 to 1.15. Synonymous variants: 752 observed, 566.93 expected, observed/expected ratio (o/e) 1.33, 90% interval 1.25 to 1.41.
Gene-disease validity (ClinGen):
ClinGen rates the evidence that GIGYF1 causes each of these diseases.
complex neurodevelopmental disorder (autosomal dominant): Definitive. A disorder that involves more than one phenotype associated with the central nervous system, including but not limited to intellectual disability, autism, and seizures (epilepsy).
Homologues: Orthologues: macaque GIGYF1 (99% identical), chimpanzee GIGYF1 (97% identical), pig GIGYF1 (94% identical), rabbit GIGYF1 (94% identical), dog GIGYF1 (93% identical), guinea pig GIGYF1 (92% identical), rat Gigyf1 (92% identical), mouse Gigyf1 (92% identical), zebrafish gigyf1a (58% identical), tropical clawed frog gigyf1 (57% identical), zebrafish gigyf1b (57% identical), Drosophila melanogaster Gyf (26% identical), and 1 more. Paralogues in human: GIGYF2 (53% identical).
Diseases named in the same sentence as GIGYF1 in open-access papers:
GIGYF1 is named in the same sentence as 28 diseases in open-access papers, as found by Europe PMC text mining. Sharing a sentence is not in itself a finding about the gene and the disease. The quoted sentences say what the papers report.
autism (7 papers, 2022 to 2025). Persistent deficits in social interaction and communication and interaction as well as a markedly restricted repertoire of activity and interest as well as repetitive patterns of behavior. "GIGYF1 gene has been proved to play an important role in the occurrence and progression of many diseases, such as autism, type 2 diabetes." (PMID 37484805, 2023). "Gigyf1 regulates ERK signaling, a pathway linked to synaptic plasticity and implicated in autism." (PMID 40295099, 2025). "To comprehensively delineate the mutation pattern and inheritance modes of GIGYF1 variants in ASD, we analyzed whole-exome sequencing (WES) or whole-genome sequencing (WGS) data from 2 autism cohorts: Simons Foundation Powering Autism Research (SPARK) and the Simons Simplex Collection (SSC)." (PMID 35917186, 2022). "Mutations in the genes encoding various factors that regulate translation (eIF4E, eIF4G1, GRB10‐interacting GYF protein 1 (GIGYF1), GIGYF2, and zinc finger protein 598) were identified in people with autism (Simons Foundation Autism Research Initiative, SFARI database)." (PMID 41236931, 2025). "Notably, recent studies have demonstrated that the conditional knockout of the GIGYF1 gene in mice disrupts IGF1R/ERK signaling pathways, resulting in autism-like behaviors, further supporting our findings." (PMID 39376742, 2024).
type 2 diabetes (6 papers, 2021 to 2024). "For example, when perturbing the enhancer linked to GIGYF1, which overlaps SNPs in the 95% credible set for a type 2 diabetes (T2D) GWAS signal, we found that GIGYF1 was significantly differentially expressed (FDR = 5.14e−14), with perturbed cells showing approximately a 10% reduction in expression." (PMID 38308274, 2024). "While GCK, HNF4A were already well-recognised as causes of maturity onset diabetes of the young (MODY), the implication of GIGYF1 was novel though was quickly confirmed in another study which had access to sequence data from 379,000 UK Biobank participants." (PMID 39666780, 2024). "Here, the authors extend genetic association analyses to rare variation using exome-sequence data from 82,277 males, finding that loss-of-function alleles in GIGYF1 are associated with six-fold higher susceptibility to both LOY and Type 2 Diabetes." (PMID 34234147, 2021). "A previous study carrying out gene-based weighed burden analysis of rare coding variants using 200,000 exome-sequenced UK Biobank participants identified three genes associated with type 2 diabetes (T2D) at exome-wide significance, GCK, HNF4A and GIGYF1." (PMID 39666780, 2024).
diabetes (4 papers, 2021 to 2024). "For the two rare-variant genes (GIGYF1 and ANKRD12) associated with alcohol consumption, GIGYF1, identified as a risk gene for diabetes in earlier research, is a protein-coding gene intricately involved in the regulation of cell growth and division." (PMID 38982111, 2024). "This direction of effect is consistent with what we see for the pLOF variants—reduced levels of GIGYF1 increases diabetes risk but increased levels of GIGYF1 are protective." (PMID 34732801, 2021). "After diabetes, the most significant disease association of GIGYF1 pLOF was with increased risk of hypothyroidism (p = 1.25 × 10–9, OR = 4.53)." (PMID 34732801, 2021). "In addition to replicating the association of GIGYF1 pLOF with T2D in an independent cohort we also used common genetic variants to further investigate the role of the GIGYF1 locus in diabetes." (PMID 34732801, 2021). "The independent glucose and T2D associations at the GIGYF1 locus and their replication in other datasets further support the hypothesis that decreasing GIGYF1 levels predisposes to diabetes while increasing GIGYF1 levels may protect from diabetes." (PMID 34732801, 2021). "We looked for more common variants that could further implicate the GIGYF1 locus in diabetes." (PMID 34732801, 2021). "Three genes from the collapsing analysis were associated with increased odds of diabetes and have been reported previously: GCK, GIGYF1, and HNF1A." (PMID 36383675, 2022). "Our results highlight the role of GIGYF1 in regulating insulin signaling and protecting from diabetes." (PMID 34732801, 2021). "These included several genes not previously implicated in diabetes, GIGYF1, TNRC6B and PFAS, as well as GCK, HNF1A and PDX1, known MODY genes." (PMID 34732801, 2021). "Notably, we uncovered novel associations for GIGYF1, a gene not previously implicated by human genetics in diabetes." (PMID 34732801, 2021). "By contrast, GIGYF1, HNF1A and HNF4A are involved with lower level cellular processes which have a less immediate impact in terms of producing diabetes as a phenotype." (PMID 39666780, 2024). "By highlighting the importance of GIGYF1 and GRB adapter proteins in modulating insulin signaling this finding may lead to new therapeutic approaches for the treatment of diabetes." (PMID 34732801, 2021). "Variants in two genes, GCK and GIGYF1, significantly associated with glucose, HbA1c and T2D diagnosis, strongly suggesting a biological role in diabetes; GCK is involved in Mendelian forms of diabetes while GIGYF1 has not previously been implicated by genetics in the disease." (PMID 34732801, 2021).
Cognitive impairment (3 papers, 2022 to 2023). Abnormal cognition is characterized by deficits in thinking, reasoning, or remembering. "Individuals with ASD with GIGYF1 LGD variants were less likely to have cognitive impairments than those with known high-confidence ASD genes (SFARI gene score = 1) (28% versus 12%, P = 8.5 × 10-24)." (PMID 35917186, 2022). "Individuals with ASD with the recurrent site had a frequency of cognitive impairments similar to that of all individuals with ASD with GIGYF1 LGD variants (15% versus 12%)." (PMID 35917186, 2022). "Among individuals with ASD, cognitive impairments were less likely in those with GIGYF1 LGD variants relative to those with other high-confidence gene mutations." (PMID 35917186, 2022). "Our analyses support that PTVs and missense variants in KDM5B, GIGYF1 and CACNA1A underlie a continuum of conditions with various degrees of cognitive impairment." (PMID 37231097, 2023). "Disruption of GIGYF1 in the developing mouse brain led to social deficits and cognitive impairments." (PMID 36189799, 2022). "In summary, our study demonstrated that haploinsufficiency of GIGYF1 in humans and mice led to core autistic behaviors with less-significant cognitive impairments." (PMID 35917186, 2022). "To explore the cognition association with GIGYF1 heterozygous LGD variants, we compared the occurrence of the parent-reported cognitive impairment in SPARK." (PMID 35917186, 2022). "Our phenotypic association analysis revealed that individuals with ASD with GIGYF1 heterozygous LGD variants shared ASD core symptoms, but with a lower prevalence of cognitive impairment." (PMID 35917186, 2022). "Although the difference was not significant, the frequency of cognitive impairment in individuals with ASD with GIGYF1 LGD variants was lower (12% versus 19%, P = 0.28) than in all individuals with ASD in SPARK." (PMID 35917186, 2022). "Haploinsufficiency of Gigyf1 (Gigyf1-heterozygous) impaired the social interactions of the mice without causing cognitive impairments, which is consistent with studies involving people with ASD." (PMID 36189799, 2022). "Indeed, our data show that the haploinsufficiency of Gigyf1 in the developing mouse brain did not contribute to learning and memory deficits associated with cognitive impairments." (PMID 35917186, 2022). "We show that haploinsufficiency of Gigyf1 in mice leads to social and behavioral disabilities without substantial cognitive impairments." (PMID 35917186, 2022). "Using a Gigyf1 conditional KO mouse model, we showed that haploinsufficiency in the developing brain led to social impairments without significant cognitive impairments." (PMID 35917186, 2022).
autism spectrum disorder (2 papers, 2022 to 2023). A spectrum of developmental disorders that includes autism, and Asperger syndrome. "GIGYF1, which is associated with Autism Spectrum Disorder (ASD) and indirectly linked to AD, as well as ADAMTSL4, involved in the metabolism of amyloidogenic peptides in AD, were both down-regulated in ACD patients." (PMID 38040763, 2023).
developmental delay (2 papers, 2021 to 2022). "Although GIGYF1 LGD variants were also identified among family members without ASD diagnoses, we found evidence of ASD/NDD endophenotypes, such as language/motor developmental delay as well as social impairment." (PMID 35917186, 2022).
Intellectual disability (2 papers, 2022 to 2024). "Moreover, ANKRD12 and GIGYF1 are well-known genes for reduced cognitive function and intellectual disability as evidenced by previous studies." (PMID 38982111, 2024). "The absence of intellectual disability is also observed in other genes (for example, SCAF1, HNRNPUL2, GIGYF1, KDM5B and KMT2C) with substantial contribution from rare inherited variants and modest effect size." (PMID 35982159, 2022).
anemia (1 paper, 2021). A reduction in the number of red blood cells, the amount of hemoglobin, and/or the volume of packed red blood cells. "GIGYF1 pLOF also associated with increased diagnosis of emphysema and anemia." (PMID 34732801, 2021).
Anxiety (1 paper, 2022). Intense feelings of nervousness, tension, or panic often arise in response to interpersonal stresses. "To determine whether Gigyf1 deficiency leads to anxiety-like behaviors in mice, we introduced the elevated plus maze test (EPM test), open field test (OF test), and light-dark box test (LDB test)." (PMID 35917186, 2022). "This is in contrast to homozygous KO Gigyf1 mice, which showed considerably more anxiety-like behaviors." (PMID 35917186, 2022). "In contrast, homozygous knockouts of Gigyf1 in the developing brain caused more severe ASD core symptoms, anxiety-like behaviors, and severe cognitive problems, consistent with a dosage effect of loss-of-function Gigyf1 mutations on phenotypic severity." (PMID 35917186, 2022).
gastric cancer (1 paper, 2023). A primary or metastatic malignant neoplasm involving the stomach. "In conclusion, the low expression of GIGYF1 gene can inhibit the occurrence and progression of gastric cancer, during which the ERK and AKT signaling pathways are inhibited." (PMID 37484805, 2023).
hypothyroidism (1 paper, 2021). Abnormally low levels of thyroid hormone. "GIGYF1 pLOF also associated with decreased cholesterol levels as well as an increased risk of hypothyroidism." (PMID 34732801, 2021). "GIGYF1 pLOF associated with a 4.5-fold increased risk of hypothyroidism and GIGYF1 is highly expressed in thyroid consistent with a biological function in this tissue." (PMID 34732801, 2021). "Given the autoimmune component in hypothyroidism and type 1 diabetes (T1D), we examined the association of GIGYF1 pLOF with T1D diagnoses but did not detect a significant association (p = 0.1)." (PMID 34732801, 2021).
leukemia (1 paper, 2019). A malignant (clonal) hematologic disorder, involving hematopoietic stem cells and characterized by the presence of primitive or atypical myeloid or lymphoid cells in the bone marrow and the blood. "Each validated gene in this category, i.e., CD3G, DFFA, GIGYF1, GIGYF2, and INTS3 were shown to play a role in neoplastic processes, including leukemia." (PMID 31709175, 2019).
viral infections (1 paper, 2024). "The depletion of SMY2-type ILE-GYF domain-containing protein 1 (EXA1), the plant homolog of GIGYF1, has also been identified as a susceptibility gene for viral infections." (PMID 39018414, 2024).
cancer (4 papers, 2019 to 2024). A tumor composed of atypical neoplastic, often pleomorphic cells that invade other tissues. "GIGYF1 plays a catalytic role in cancer progression, such as gastric cancer and malignant glioma." (PMID 38733530, 2024). "PPPGΦ motifs tend to interact with GYF domain proteins, such as the GIGYF1/2 translational repressors that were described to bind CAF40 in human cancer cells." (PMID 30692204, 2019). "Previously, GIGYF1 has been mostly used in studies on nerve damage and has not been involved in the field of cancer." (PMID 38733530, 2024). "Similarly, the Smy2 homologs GIGYF1 and -2 affect the transcription stress response in human cells and regulate the function of the Cdc48 homolog VCP/p97, presently being explored as a target for cancer therapy." (PMID 36288698, 2022).
tumor (4 papers, 2022 to 2024). "In conclusion, GIGYF1 gene is highly expressed in GC tumor tissue, and low expression of GIGYF1 can inhibit the occurrence and progression of GC." (PMID 37484805, 2023). "The experimental results showed that GIGYF1 gene was highly expressed in GC tumor tissue and was related to tumor size and TNM stage." (PMID 37484805, 2023). "The results showed that the expression of GIGYF1 in 31 of the 42 (15/22; 73.81%) pairs of tissue samples was higher than that in the paracancer tissue samples, which was related to tumor size and TNM stage." (PMID 37484805, 2023). "We collected 42 pairs of GC patients' tumor tissue samples and paracancer tissue samples, and detected the expression of GIGYF1 in the tissue samples by real-time fluorescent quantitative PCR." (PMID 37484805, 2023). "GIGYF1 gene expression was higher in tumor tissue samples than in paracancer tissue samples, and higher in human GC cell lines than in human normal gastric epithelial cells." (PMID 37484805, 2023). "The expression level of GIGYF1 protein in 12 pairs of tumor tissue samples and paracancer tissue samples was detected by western blotting, and proved that the expression level of GIGYF1 protein in tumor tissue samples was generally higher than that in paracancer tissue samples." (PMID 37484805, 2023). "As for others, CTC, GIGYF1, MTUS2, POM121, PTP14, SPOPL, and ZNF 208 were detected only in tumor tissue, and none were determined to be pathogenic by both algorithms concordantly." (PMID 38254245, 2024). "In conclusion, suppressing circPDK1 inhibits proliferation and invasion of PTX-resistant cells, accelerates apoptosis, and acts as a molecular sponge of miR-4731-5p to downregulate GIGYF1, promote PTX sensitivity of NSCLC cells, and thus inhibit tumor growth in vivo." (PMID 38733530, 2024).
infection (1 paper, 2024). The state of being infected such as from the introduction of a foreign agent such as serum, vaccine, antigenic substance or organism. "Notably, enhanced expression of TTP, which enables recruitment of GIGYF1 to Ifnb1 mRNA, has been observed upon infection with several types of viruses." (PMID 39018414, 2024).
GIGYF1 also shares sentences with these, for which no sentence is quoted: breast carcinoma (2 papers); Alzheimer disease (1); behavior problems (1); emphysema (1); Hyperglycemia (1); Hypoglycemia (1); lipodystrophy (1); maturity-onset diabetes of the young (1); motor developmental delay (1); non-small cell lung carcinoma (1); schizophrenia (1); urinary system disorder (1).